SF1 (splicing factor 1)
Diseases named in the same sentence as SF1 in open-access papers (continued):
Sharing a sentence is not in itself a finding about the gene and the disease.
Adrenal insufficiency (16 papers, 2008 to 2024). Insufficient production of steroid hormones (primarily cortisol) by the adrenal glands. "The 2–3 loop is the site of polymorphisms found in patients presenting with adrenal insufficiency, ovarian insufficiency, male infertility, and disorders of sexual development, all attributed to loss of SF-1 function in these patients." (PMID 33933440, 2021). "SF1 is a true effector of cell fate as it initiates a genetic program driving embryonic mesenchymal cells toward a steroidogenic phenotype/lineage, and SF1 mutations can result in adrenal insufficiency." (PMID 29386111, 2018). "To date, only three SF-1 mutations have been implicated with adrenal insufficiency (heterozygote Gly35Glu and Arg255Leu, homozygote Arg92Gln)." (PMID 25122490, 2014). "Human NR5A1/SF-1 mutations cause 46,XY disorder of sex development (DSD) with broad phenotypic variability, and rarely cause adrenal insufficiency although SF-1 is an important transcription factor for many genes involved in steroidogenesis." (PMID 25122490, 2014). "SF-1 is involved in the regulation of steroidogenesis, and SF-1 gene mutation causes adrenal insufficiency and XY sex reversal (46, XY karyotype, normal female external genitalia, streak gonads, azoospermia, and the presence of normal Müllerian structures) in a phenotypically female child." (PMID 35495001, 2022). "Compromised development of the X-zone is seen in other mouse models of adrenal insufficiency, including those with Sf1 mutations, suggesting that SGPL1 may also have a role to play in the developing human adrenal." (PMID 28165343, 2017). "So far, only two additional SF-1 mutations causing adrenal insufficiency have been reported." (PMID 25122490, 2014). "Previous study for heterozygous NR5A1+/− mice only revealed adrenal insufficiency during stress conditions and showed significant adrenal hyperplasia, demonstrating that normal gene dosage of SF-1 is required for mounting an adequate stress response." (PMID 30425642, 2018). "Glu7Stop and His408Profs*159 are novel SF-1 mutations identified in patients with 46,XY DSD and adrenal insufficiency (Glu7Stop)." (PMID 25122490, 2014). "The first human individual with a heterozygote Gly35Glu SF-1 mutation had 46,XY DSD and adrenal insufficiency." (PMID 25122490, 2014). "Identification of the transcription factor SF-1 as an important metabolic regulator was established by the Parker group while studying germline SF-1 KO mice which exhibit neonatal lethality due to adrenal insufficiency." (PMID 23675313, 2013). "Although occasional cases of adrenal insufficiency linked to disruptive variants in SF-1/NR5A1 were subsequently identified, it seemed likely that SF-1-associated conditions would ultimately be confined to the category of “biologically interesting, but very rare”." (PMID 38281359, 2024). "In this study, two novel SF-1 mutations (Glu7Stop, His408Profs*159) were identified in 5 patients with SF-1 deficiency, all manifesting with 46,XY DSD and one (Glu7Stop) presenting with adrenal insufficiency that is rarely associated with SF-1 mutations." (PMID 25122490, 2014). "Glu7Stop is the 4th reported SF-1 mutation causing DSD and adrenal insufficiency." (PMID 25122490, 2014). "Our case report, while not demonstrating a genetic aetiology (polymorphism of SF1 was the only abnormality), gives evidence of a possible genetic primary cause of adrenal insufficiency, based on clinical and laboratory examinations and the age of onset." (PMID 25255796, 2014). "Finally in 1999, the first human being with adrenal insufficiency and 46,XY disorder of sexual development (DSD) harboring a heterozygote SF-1 mutation was described." (PMID 25122490, 2014). "Similarly to Insr;Igf1r mutant embryos, Sf1 haploinsufficient mice exhibit adrenal insufficiency due to a severe reduction of adrenocortical precursors within the AGP, but show no change in the number of gonadal precursors." (PMID 23300479, 2013).
Adrenal insufficiency (continued). "The clinical differentials of sex reversal with adrenal insufficiency include P450scc deficiency due to mutations in CYP11A1 gene, Smith-Lemli-Opitz syndrome (DHCR7 gene), NR5A1 (SF1) mutation-related sex reversal, CYP17 and 3-beta hydroxysteroid dehydrogenase deficiency (HSD3B2 gene)." (PMID 23748066, 2013). "Here, we present five novel heterozygous SF1 mutations in a cohort of 27 46,XY patients (18.5%) with severe underandrogenization but without adrenal insufficiency." (PMID 17694559, 2008). "Given the importance of SF-1 in adrenal development, the next obvious question to address was whether SF-1 changes could be detected in girls (46,XX) who present with primary adrenal insufficiency or in patients with adrenal insufficiency where no specific cause had been found." (PMID 21078366, 2011). "In addition to defects in testis differentiation, we found that double heterozygous Wt1+/−; Sf1+/− fetuses lacked adrenal glands and that neonates die shortly after birth, presumably from adrenal insufficiency." (PMID 22496664, 2012).
pituitary adenomas (16 papers, 2013 to 2025). "In 2017, the World Health Organization (WHO) updated the classification of pituitary adenomas with the addition of transcription factors SF1, PIT1, and TPIT to better delineate adenohypophyseal cell lineages." (PMID 39859246, 2025). "The most common patterns of multiple pituitary adenomas are PIT-1-lineage combined with SF-1-lineage, followed by PIT-1-lineage combined with TPIT-lineage, which were in keeping with our findings." (PMID 38756997, 2024). "The expression of both PIT-1 and SF-1 was previously shown in rare double pituitary adenomas that are composed of multiple PitNETs in one tumor." (PMID 36497102, 2022). "In vitro studies demonstrated for the first time that Cyp11a1 is a target of SF-1 in gonadotroph cells and promotes proliferation/survival of rat pituitary adenoma primary cells and cell lines." (PMID 23756599, 2013). "Transcription factor staining thus divides pituitary adenomas into three distinct subgroups, where SF1 is expressed in gonadotroph adenomas, PIT1 is expressed in GH- (somatotroph), PRL-, and TSH-producing adenomas, and TPIT is expressed in corticotroph adenomas." (PMID 39859246, 2025). "The pituitary-specific transcription factors, including PIT-1, T-PIT, SF-1, and GATA-2, involved in adenohypophysial cell differentiation and maturation are now regarded as key diagnostic tools for the further characterization of pituitary adenomas." (PMID 36060980, 2022). "The current WHO classification of PitNETs or pituitary adenomas is based on the expression of pituitary-related transcription factors such as PIT1, SF-1, TPIT, and anterior pituitary hormones." (PMID 39816322, 2024). "Within patients with a pituitary adenoma, the influence of transcription factors (T‐PIT, SF‐1 and PIT‐1) and Ki‐67 index on presence and impact of pre‐ and postoperative headache was determined." (PMID 39001600, 2024). "Based on these findings, the fourth edition of WHO classification system proposed a cell lineage-based classification scheme for pituitary adenomas, in which TFs such as PIT-1, T-PIT, and SF-1 serve as key classifiers." (PMID 34589436, 2021). "The incidence of PIT1/SF1 tumors varies across studies and ranges from 0.5% to 8% in studies conducted on all types of pituitary adenomas with or without function." (PMID 40421250, 2025). "According to the 2022 WHO classification, clinically nonfunctional pituitary adenomas include SF1‐lineage tumors, silent TPIT‐lineage tumors, null cell tumors, and some PIT1‐lineage tumors." (PMID 37661840, 2023). "Unfortunately, since most pituitary adenomas are quite small in size, there are not enough samples left for further test of SF-1 expression to make accurate classification." (PMID 31455412, 2019). "All pituitary adenomas are divided into the three following lineages: lactotroph, somatotroph, and thyrotroph belong to PIT-1 (pituitary-specific TF 1), corticotroph belongs to T-PIT (pituitary cell-restricted factor), and gonadotroph belongs to SF-1 (steroidogenic factor 1)." (PMID 34589436, 2021). "Among 50 patients with pituitary adenomas whose pathological examinations were discrepant between transcription factor stains and pituitary hormone stains, the majority of mismatched cases were gonadotroph adenomas (43 patients, 86.0%) with stains positive for SF-1 but negative for both FSH and LH." (PMID 34589436, 2021).
Infertility (12 papers, 2009 to 2025). "The disruption of SF1 usually causes testicular dysgenesis, a reduction in androgen production, and male factor infertility." (PMID 38539974, 2024). "In humans, variants in SF1 manifest with a wide spectrum of different phenotypes such as hypospadias, microphallus, infertility, undescended testis, female external genitalia and/or testicular dysgenesis in 46, XY DSD patients." (PMID 31719618, 2019). "A novel heterozygous missense variant, c.584C > T (p.Ser195Phe), located in a highly conserved region of the SF-1 protein, was identified and found to be associated with severe infertility phenotypes, including micropenis, testicular hypotrophy, and azoospermia." (PMID 41386844, 2025). "The mammalian NR5A homolog SF-1, is expressed in somatic follicle cells of the ovary in both rodents and humans, and loss of this SF-1 expression in murine granulosa cells leads to a severe depletion of developing follicles and infertility." (PMID 32338596, 2020). "In the same line, de novo SF1 activation, in vivo, promotes aberrant endometrial glands morphogenesis, leading to endometrial architecture disrupting and infertility." (PMID 40792071, 2025). "While rare deleterious NR5A1/SF-1 variants have been identified in individuals with various differences of sex development (DSD), primary ovarian insufficiency, and infertility, their impact on the general population remains unclear." (PMID 39479520, 2024). "But, NR5A1/SF-1 variants can also be identified in individuals without DSD, including healthy carriers, infertile men, or women with primary ovarian insufficiency (POI)." (PMID 39479520, 2024).
Anxiety (9 papers, 2011 to 2025). Intense feelings of nervousness, tension, or panic often arise in response to interpersonal stresses. "The VMH, especially its steroidogenic factor-1 (SF-1)-expressing neuronal subpopulation, is strongly associated with affective disorders such as anxiety and fear." (PMID 38161999, 2023). "Taken together, we concluded that astrocytes regulate SF-1 neuronal activity, which, in turn, regulates anxiety-like behavior and bone loss via NMDA receptors." (PMID 34306063, 2021). "Therefore, consistent with our optogenetic and chemogenetic studies, feeding behavior was associated with low while anxiety was associated with high intrinsic SF1 activity." (PMID 29262334, 2017). "Steroidogenic factor-1 (SF-1)-positive neurons in the VMHvl regulate anxiety levels in mice, and the ablation of SF-1 neurons in the VMHvl reduces the level of anxiety in mice." (PMID 40721553, 2025). "Our data support that VMH astrocytes regulate SF-1 neuronal activity through the NMDA receptor, which regulates anxiety and bone loss induced by chronic stress." (PMID 34306063, 2021). "Central nervous system-specific knockout of Sf1 in mice leads to increased anxiety-like behaviours, whilst more recently, down-regulation of glutamatergic output from the VMN, which harbours Sf1-positive neurons, was shown to have an anxiety-reducing effect." (PMID 28334933, 2017). "Ablation of SF1+ neurons significantly reduced measures of anxiety in each of the three different assays." (PMID 25748136, 2015). "To do this, we compared the behavior of males with ablated SF1+ neurons vs controls in three different anxiety assays: the elevated plus maze, novel object test, and the light–dark box." (PMID 25748136, 2015). "Thus, SF-1 neurons in the VMH are crucial for central regulation of anxiety and bone metabolism." (PMID 34306063, 2021). "Lastly, we tested whether SF1+ neurons play an essential role in anxiety." (PMID 25748136, 2015). "Thus, SF1+ neurons are required for either the induction or expression of anxiety (or both)." (PMID 25748136, 2015). "Along with their key role in the regulation of metabolism, SF1-expressing neurons have been proposed to control the development of psychiatric-like behavior since SF1 controls the transcription of cannabinoid receptor 1 and SF1 knock-out mice present anxiety-like features." (PMID 25271967, 2014). "In addition, a recent clinical study from patients with SF1 (Nr5a1) gene mutations show psychiatric symptoms including excessive anxiety and/or depression, suggesting that SF1 and the VMH may have roles in both anxiety- and depressive-like behaviors." (PMID 25271967, 2014). "Furthermore, cannabinoid and serotonin receptors in steroidogenic factor-1- (SF-1-) positive neurons, the main neuronal subtype in the VMH, mediate regulation of anxiety behavior in mice." (PMID 34306063, 2021). "The role of ff1b in the zebrafish hypothalamus has not been determined, but in mice, hypothalamic Sf1 governs anxiety behaviours." (PMID 28334933, 2017). "Previous studies in adult SF-1 KO and in VMH-specific SF-1 KO showed that structural changes in the VMH could result in impaired social behaviors, such as anxiety, aggression, and female sexual behavior, in addition to impairment in energy balance regulation." (PMID 27445727, 2016).
Hypoglycemia (9 papers, 2013 to 2025). A decreased concentration of glucose in the blood. "Hypoglycemia-associated up-regulation of this gene profile was amplified by SF-1 siRNA pretreatment." (PMID 39401164, 2024). "Hypoglycemia caused a corresponding gain or loss of SF-1 control of Ghrh and GLS gene transcription." (PMID 39401164, 2024). "There is, above all, an urgent need to understand if SF-1 – dependent changes in ER variant-mediated estradiol signaling to Ghrh neurons during hypoglycemia are involved in neurotransmitter protein marker gene responses to glucose imbalance." (PMID 39024550, 2024). "Data show that microdissected VMNdm tissue exhibited hypoglycemia-associated reductions in VMNdm SF-1 protein; SF-1 siRNA pretreatment amplified this decline in protein expression." (PMID 39401164, 2024). "SF-1 regulation of glucagon release is evidently glucose-dependent as hypoglycemia causes loss of transcription factor control of this hormone profile." (PMID 39401164, 2024). "The mechanisms that underlie this evident hypoglycemia-associated gain in SF-1 inhibitory control remain unclear." (PMID 39401164, 2024). "There remains a critical need for insight on how SF-1—dependent adjustments in ER variant-controlled estradiol input to VMNdm Ghrh neurons during hypoglycemia may contribute to transmitter protein marker gene responses to that metabolic challenge." (PMID 39401164, 2024). "Further studies are needed to address whether VMN NOS and/or SF‐1 neurons may respond exclusively to hypoglycemia‐associated glycogen exhaustion or are activated by depletion of this reserve regardless of initiating circumstances." (PMID 29199177, 2017). "In summary, present studies applied in vivo gene silencing and single-cell laser catapult microdissection/multiplex qPCR analytical tools to address the premise that Ghrh-R may regulate ER variant-specific estradiol input to VMNdm Ghrh/SF-1 neurons during eu- and/or hypoglycemia, according to sex." (PMID 40534773, 2025). "It would be informative to determine if hypoglycemia-associated changes in VMNdm Ghrh/SF-1 neuron uptake and metabolism of glucose and/or nerve cell energy stability may affect the volume or direction of activity of Ghrh-R-sensitive signal transduction pathways according to sex." (PMID 40688570, 2025). "Data show that in females, hypoglycemia elicits a gain of SF-1 inhibitory control of VMNdm Ghrh neuron Ghrh and Ghrh-receptor gene profiles and loss of augmentation of glutaminase transcription; SF-1 gene silencing diminished eu- and hypoglycemic patterns of neuronal nitric oxide gene transcription." (PMID 39401164, 2024). "The outcomes here bolster the role of glucose status as a determinant of Ghrh/SF-1 signaling as Ghrh-R regulation of proportionate target gene expression is evidently variable between eu- versus hypoglycemia, albeit in a sex-specific manner." (PMID 40688570, 2025). "Female VMNdm Ghrh/SF-1 neurons exhibit an apparent gain in positive Ghrh-R regulatory tone during hypoglycemia." (PMID 40688570, 2025). "Aromatase gene expression is higher in male versus female VMNdm Ghrh/SF-1 neurons and is inhibited by hypoglycemia in male rats alone." (PMID 40534773, 2025). "Recent studies document Ghrh control of hypoglycemia-sensitive counterregulatory neurotransmitter expression in dorsomedial VMN (VMNdm) Ghrh/steroidogenic factor-1 (SF-1) neurons." (PMID 40688570, 2025). "Ghrh and Ghrh receptor transcripts were correspondingly refractory to or increased by hypoglycemia, yet SF-1 knockdown decreased both gene profiles." (PMID 39024550, 2024). "SF-1 gene expression in this nerve cell type was reduced in response to hypoglycemia; INS-injected animals exhibited further reductions in this mRNA profile as a consequence of SF-1 siRNA pretreatment." (PMID 39024550, 2024).